AR (androgen receptor)
Diseases named in the same sentence as AR in open-access papers (continued):
Sharing a sentence is not in itself a finding about the gene and the disease.
prostate carcinoma (continued). "Furthermore, mTOR and EGFR co-inhibition with everolimus and gefitinib has shown limited sensitivity in patients owing to enhanced AR activity and PSA levels, providing further rationale for combining AR and PI3K-AKT-mTOR blockade to treat prostate cancer." (PMID 32630372, 2020). "These first-generation nonsteroidal AR antagonists are effective for most prostate cancer patients, but castration-resistant prostate cancer (CRPC) often develops after a few years, due to the mutation of AR." (PMID 32759847, 2020). "Strong associations with cellular proliferation genes and select pathogenesis factors independent of AR implicate CENPA as a contributor to a biological process that is involved in androgen refractory prostate cancer progression." (PMID 32371391, 2020). "Treatment of SP-2509 suppressed prostate cancer migration, and metastasis independent of AR expression." (PMID 33343366, 2020). "While AR’s function has not been fully characterized in breast cancer, work done in prostate cancer informs the potential function of AR in breast cancer." (PMID 33062889, 2020). "Thus, AR and PARG are engaged in reciprocal regulation suggesting that the success of androgen ablation therapy can be enhanced by PARG inhibition in prostate cancer patients." (PMID 32123273, 2020). "Ralaniten and EPI-7170 sensitized prostate cancer cells that express full-length AR and AR-Vs to radiotherapy whereas enzalutamide had no added benefit." (PMID 32708219, 2020). "Due to AR is a carcinogen in prostate cancer, next we tested the correlation in two prostate cancer cell line (DU145 and PC3) and no significant changes were observed." (PMID 32579541, 2020). "Since CYP3A5 is the major extrahepatic CYP3A isoform expressed in prostate and regulates AR activation, the presence of these SNPs in CYP3A5 may alter prostate cancer occurrence growth and treatment resistance in a race-dependent manner." (PMID 32316460, 2020). "In both androgen-dependent and -independent prostate cancer cells, resveratrol inhibits AR transcriptional activity, but does not affect the total and nuclear AR levels." (PMID 32326308, 2020). "Interestingly, the PI3K-AKT-mTOR, WNT, MAPK and AR signaling cascades all converge to regulate the transcription factor MYC, which is frequently amplified in prostate cancer/mCRPC." (PMID 32630372, 2020). "The organoids biobank of metastatic prostate cancer covering both AR (androgen receptor)-positive and -negative subtypes was the first reported biobank established by Gao and colleagues." (PMID 33135109, 2020). "Interestingly, studies employing xenograft prostate tumor models have shown that castrate-resistant prostate cancer (CRPC) tumors that emerge after androgen-ablation therapy, continue to express AR and AR-regulated genes." (PMID 32820253, 2020). "On the other hand, many reports suggested the tumor suppressive role of miR-205 as ectopic expression of miR-205 diminished the Androgen Receptor (AR) and the Mitogen-Activated Protein Kinase (MAPK) signaling pathways, and further inhibited the tumor development in prostate cancer." (PMID 32854238, 2020). "For instance, polycomb repressive complex 1 (PRC1) promotes metastasis of double negative [androgen receptor (AR) and neuroendocrine] prostate cancers by CCL2 expression, which regulates TAM self-renewal and recruitment." (PMID 32971847, 2020). "Systematic observation of ERa/PR/AR ColNu mIHCF of prostate cancer with lower magnification (20×) enabled certain areas where nuclear AR was present in the absence of ERa to be distinguished." (PMID 33266334, 2020). "The prostate cancer cell lines used in those studies can be divided into androgen receptor (AR)-positive (LNCaP and 22RV1) and AR-negative (DU-145 and PC-3)." (PMID 33143283, 2020). "In prostate cancer, selective FASN inhibition antagonizes tumor growth through metabolic reprogramming and results in a reduced protein expression and reduced transcriptional activity of AR." (PMID 32103349, 2020).
prostate carcinoma (continued). "Prostate cancer cells exhibit rapid proliferation responses in response to androgen stimulation, suggesting non-genomic AR signaling." (PMID 33062889, 2020). "In addition, cyclin-dependent protein kinase 9 (CDK9) is a druggable target for prostate cancer because CDK9 can not only phosphorylate AR and activate AR transcriptional activity but also target anti-apoptotic proteins." (PMID 32456317, 2020). "In two different methods, one being stimulated by increased AR signaling and the other being induced by inflammatory cytokines in response to taxane treatment, the PI3K/Akt pathway and hyperactivation of the pathway lead to resistance in prostate cancer." (PMID 33182737, 2020). "The PMEPA1 gene is an important regulator of AR and TGF-β signaling in prostate cancer cells." (PMID 32842649, 2020). "For example, MET is highly expressed in AR-negative prostate cancer cell lines such as PC3 and DU145, however, it is downregulated in AR-positive cell lines (LNCaP, LAPC-4, CWR22, and LuCaP)." (PMID 32290402, 2020). "To further validate the tumor-suppressing role of HNF4α in prostate cancer cell growth, we next generated stable HNF4α-transduced infectants in AR-negative PC-3 and AR-positive LNCaP cells for growth phenotype characterization." (PMID 31695151, 2020). "Thus, given the importance of CHK2 and AR to the DDR and prostate cancer growth, a full understanding of the functional consequences of the CHK2–AR interaction is required, with the hope of possible clinical applications towards CRPC." (PMID 32579110, 2020). "In the case of prostate cancer, increased ATAD3A correlates with tumor grade, disease status, lymphovascular infiltration, serum PSA levels, as well as expression of the androgen receptor (AR)." (PMID 33113782, 2020). "In summary, these data reveal that blocking the transcriptional activities of both full-length AR and truncated AR-Vs with ralaniten inhibits the expression of DDR genes, cell proliferation, as well as cell survival, thereby leading to increased sensitivity of prostate cancer to radiotherapy." (PMID 32708219, 2020). "AR regulates the expression of many genes in prostate cells including those controlling cellular proliferation and survival thereby providing the rationale for ADT to block AR signaling as a systemic therapy for prostate cancer." (PMID 32708219, 2020). "Similar to non-genomic AR functions in prostate cancer, the cytoplasmic roles of AR have also been investigated in breast cancer." (PMID 33062889, 2020). "Presently, we demonstrated the mechanism by which SETD1A regulates the FOXM1 pathway and showed that it does not affect the AR pathway in prostate cancer cells." (PMID 32629770, 2020). "In prostate cancer, CREB5 could improve resistance to enzalutamide with the help of FOXA1 and selectively enhance the interaction of AR with target genes critical for survival." (PMID 32843066, 2020). "After elucidating the mode of action, it was found that our DHC acts by inhibiting AKR1C3 and by antagonizing the androgen receptor noncompetitively, thus exerting strong antiandrogenic signaling in the prostate cancer cell." (PMID 32993084, 2020). "Since the expression of CYP11A1 is rather low in prostate cancer cells and hardly detectable in clinical prostate cancer tissues, we next manly investigated the significance of ERRα-enhanced AKR1C3 expression or activity in the DHT biosynthesis in AR-positive prostate cancer cells." (PMID 32226548, 2020). "As a result of the absence of regulation functions on AR/TGF-β signaling of PMEPA1-c isoform in prostate cancer cells, we focused on the study of clinical significance and relevance of PMEPA1 isoforms (d and e) in prostate cancer patients." (PMID 32064040, 2020). "We identified the prostate cancer CTCs based on their positive immunostaining for androgen receptor (AR) and cytokeratin 8, 18, and 19 (Cy) and negative staining for CD45." (PMID 32784507, 2020).
prostate carcinoma (continued). "The growth of prostate cancer cells is relevant to the androgen level; therefore, androgen deprivation therapy (ADT), a treatment to reduce androgen levels and/or block androgen receptor activity, has been introduced to most early-stage prostate cancer patients." (PMID 32545675, 2020). "Recently, our study clarified that PMEPA1-a and PMEPA1-d were PMEPA1 isoforms promoting the cell growth, cell plating efficiency and colony forming capacity in soft agar of AR negative prostate cancer cells." (PMID 32842649, 2020). "The accumulation of γH2AX by SPOP knockdown was observed in prostate cancer cell lines that were AR-positive (LNCaP cells, C4-2 cells), but not in those that were AR-negative (PC3 cells, DU145 cells)." (PMID 33023230, 2020). "AR plays a negative role in regulating the autophagy induced by celastrol, and it inhibits autophagy by transactivating mir-101 in prostate cancer cells." (PMID 32265986, 2020). "STEAP2 has been detected in androgen receptor (AR)-negative and (AR)-sensitive prostate cancer cell lines." (PMID 32290196, 2020). "In this study we focused on whether genomic and pharmacological inhibition of AR expression and AR activity, respectively, could regulate global ASE in prostate cancer cells." (PMID 32820253, 2020). "In addition, in breast cancer, like ADP, the FASN expression is correlated with the HER2 status and the subtype of the immunoprofiling classification, and in prostate cancer, the FASN expression is correlated with the AR expression." (PMID 32103349, 2020). "We also found that AR was reexpressed in xenograft tumors derived from both CSCs and parent cells of PC3, further demonstrating that the candidate CSCs are able to differentiate in vivo to generate tumors with features of prostate cancer." (PMID 31942000, 2020). "Other known prostate cancer phenotypes include neuroendocrine (NE) and small cell prostate cancer that are characterized as AR negative and appear as highly aggressive disease forms." (PMID 32585812, 2020). "Additionally, the fact that signaling through the androgen receptor (AR) axis facilitates prostate cancer development, suggests a relationship between TMPRSS2 and prostate cancer." (PMID 32974166, 2020). "Furthermore, AR regulation of PARG expression was confirmed by quantitative RT-PCR and western blotting in two independently derived prostate cancer cell lines." (PMID 32123273, 2020). "Preclinical data have shown potential synergy of PARP inhibitors and androgen receptor antagonists irrespective of HRR status in prostate cancer." (PMID 32117762, 2020). "First-generation nonsteroidal androgen receptor (AR) antagonists, such as flutamide (2a) and bicalutamide, are effective for most prostate cancer patients, but resistance often appears after several years due to the mutation of AR." (PMID 32759847, 2020). "Additionally, in prostate cancer cells, the synthetic androgen mibolerone inhibited proliferation and reduced levels of c-MYC transcripts, suggesting that AR is important for regulating c-MYC levels." (PMID 33062889, 2020). "On the other hand, PMEPA1-d promoted the growth of AR negative prostate cancer cells in TGF-β signaling dependent way." (PMID 32064040, 2020). "We next leveraged publicly available (GSE110903) RNA-seq data to further study the effects of genomic inhibition of AR on ASE in MDA-PCa-2b cells, a model for advanced prostate cancer (advPC) bone metastasis cells that express PSA, AR, and are androgen sensitive." (PMID 32820253, 2020). "In prostate cancer, despite new treatments for castration-resistant prostate cancer (CRPC), the prognosis of patients with CRPC remains bleak due to acquired resistance to androgen receptor (AR)-directed therapy." (PMID 33542904, 2020). "However, the region gains enhancer activity in prostate tumors and in the prostate cancer cell line, LNCaP as seen by the presence of DHS, H3K27ac, FOXA1, and AR occupancies." (PMID 32680982, 2020).
prostate carcinoma (continued). "Prostate cancer cells that express AR-Vs either alone or together with full-length AR do not exhibit synergism between ADT and radiotherapy that is observed in cells that express solely full-length AR." (PMID 32708219, 2020). "Although AR-induced cellular functions are vital for early development and physiological regulations, excessive AR activation triggered by xenobiotic agonists accelerates diseases severity such as androgen insensitivity syndrome (AIS) and prostate cancer." (PMID 33106158, 2020). "Furthermore, AR positive cell lines appear more sensitive to IKBKE inhibition upon comparison of GI50 values and ‘normal’ prostate cancer cells appear to be less sensitive." (PMID 32324216, 2020). "Human patient samples (both primary tumor and bone metastases), human prostate cancer cell lines and transgenic mouse models of prostate cancer have consistently demonstrated that AKT-mTOR signaling is increased in response to androgen/AR-directed blockade." (PMID 32630372, 2020). "An AR mediated lncRNA ZEB1-AS1 can promote cell stemness, proliferation, and invasion of cholangiocarcinoma, while AR inhibited lncRNA TMPO-AS1 can facilitate cell proliferation and migration, and correlate with poor prognosis in prostate cancer." (PMID 32661324, 2020). "Moreover, a genome-wide analysis on AR in prostate cancer cells revealed that BRACHYURY binding motif is highly enriched in AR-bound promoter region, suggesting that BRACHYURY is involved in AR regulation on target." (PMID 32695672, 2020). "Although the identification of a metabolic phenotype of cancer cells is not recent, the effects of androgen/AR-signaling on prostate cancer cell metabolism are emerging and remain to be elucidated." (PMID 32927797, 2020). "Finally, we show in laser capture microdissected human prostate cancer samples and the prostate TCGA cohort that MEIS1 expression is inversely proportional to AR activity as well as HOXB13, a known interacting protein of both AR and MEIS1." (PMID 32681068, 2020). "Besides, because anticarcinogenic properties of naringenin have been reported in diverse malignant tumors prostate cancer pathway consisting of eight proteins was found: AKT1, MAPK1, IGF1R, AR, CCND1, INS, PIK3CA, IGF1." (PMID 30918758, 2019). "It has been reported in the literature that in prostate cancer, ROR-γ could promote the expression of AR by transcription, and the application of an ROR-γ antagonist had an effect on the castration of prostate cancer." (PMID 31413736, 2019). "Taken together, these studies indicate that the NRs in subfamily 0 play an antioncogenic role in prostate cancer partially through an inhibitory effect on AR, which may be mediated by their interactions with the LBD of AR." (PMID 31212954, 2019). "This complex has a crucial activity in a castration-resistant LNCaP derivative prostate cancer cell line, suggesting that the new therapies acting on non-genomic AR signalling can find a potential clinical application." (PMID 30832393, 2019). "Moreover, TGF-β upregulates AR signaling via activation of Twist1, which results in the induction of EMT and stimulation of invasiveness of prostate cancer cells." (PMID 31842336, 2019). "Tip60 is an androgen receptor co-activator acting via direct acetylation of lysine residues within the KLKK motif of the receptor hinge region, which is overexpressed in aggressive cases of prostate cancer." (PMID 31671779, 2019). "The number of metastatic lung lesions decreased after the administration of resveratrol in a xenograft mouse model of prostate cancer obtained from an aggressive AR-negative cancer cell line." (PMID 30823649, 2019). "Furthermore, a study regarding to androgen receptor splice variant AR-V7 indicated that DDX39B could serve as the accelerator of AR-V7 mRNA expression and escalated DDX39B could result in resistance to androgen deprivation therapy and poor prognosis in patients with prostate cancer." (PMID 31681747, 2019).
prostate carcinoma (continued). "RSV did not oppose all transcriptional changes induced by androgens indicating that RSV protection against prostate cancer is not strictly attributable to repression of AR expression." (PMID 30832393, 2019). "On the contrary, prostate-cancer-specific enhancers had motifs for FOXA1, GRHL2, AR, and ETS." (PMID 31515496, 2019). "To figure out if the effect of FRG1 expression on prostate cancer cells is irrespective of androgen receptor status, we used LNCaP cell lines with ectopic expression of FRG1 and depletion of FRG1 along with their controls, for cell based assays." (PMID 30975102, 2019). "On the other hand, enzalutamide is not effective in activated AR without ligand binding domain of prostate cancer cells." (PMID 31731466, 2019). "However, prostate cancer patients receiving androgen deprivation therapy often relapse and develop castration-resistant prostate cancer (CRPC), which still relies on the AR pathway for growth." (PMID 30774773, 2019). "Western blots detected high endogenous levels of both ESRP1 and ESRP2 proteins within the AR positive LNCaP and CWR22 RV1 prostate cancer cell lines, as compared to the AR negative PC3 and DU145 prostate cancer cell lines." (PMID 31478829, 2019). "LASCPC-01 is an SCNC prostate cancer cell line with N-Myc gene as a driver but does not express the androgen receptor." (PMID 31035489, 2019). "In prostate cancer, besides PARP inhibition, the targeting of DDR molecules such as ATM/ATR might be explored also in combination with chemotherapy, immunotherapy, and AR-targeted agents." (PMID 31242618, 2019). "In fact, prostate cancers contain both AR+ and AR-low-expressing nonexpressing (AR-/low) and is augmented in advanced and relapsed prostate cancers." (PMID 31366128, 2019). "AR was characterized as a critical transcriptional factor in prostate tumorigenesis, and mTORC1 has been found to participate in EMT (Epithelial mesenchymal transition) in prostate cancer." (PMID 31142324, 2019). "The inhibition of USP7, able to affect the stability of the AR isoforms but also that of proteins like CCDC6 involved in HR impairment, might be able to sensitize hormone-sensitive and hormone-resistant prostate carcinoma to PARP inhibition." (PMID 31242618, 2019). "Accordingly, H3K27ac ChIP-seq profiles show that multiple enhancers found within a TAD where the promoter of AR gene is located are active in 22Rv1 prostate cancer cells, but not in RWPE1 normal cells." (PMID 31515496, 2019). "We had previously demonstrated that EGCG inhibits CK2 in prostate cancer cells, which may represent an additional mechanism of EGCG activity on AR function." (PMID 31197122, 2019). "Due to the lack of the LBD, its activity is insensitive to the AR antagonists, bicalutamide and enzalutamide, agents currently used as prostate cancer therapeutics." (PMID 30664691, 2019). "DU145 and PC3 prostate cancer cells (both AR negative and GR positive) were serum-starved and then treated with Sema4D (2 μg/mL), dexamethasone (10 nM) or vehicle for 60 min." (PMID 31861264, 2019). "Kaempferol inhibits cell proliferation and promotes apoptosis of prostate cancer cell lines significantly, especially LNCaP cells, which is an AR-positive prostate cancer cell line, compared with noncancer cells lines, such as RWPE-1." (PMID 31871879, 2019). "Apalutamide is a next-generation non-steroidal androgen receptor antagonist being studied in patients with metastatic castration-resistant prostate cancer and further results and analysis would be needed to investigate its impact on bone health [41••]." (PMID 31760582, 2019). "Alternatively, AR can also be regulated by different signaling pathways such as MAPK/ERK, AKT, PI3K/AKT/mTOR, and WNT signaling in the development and tumorigenesis of prostate cancer." (PMID 31395805, 2019).